KBTBD2 (kelch repeat and BTB domain containing 2)
Description:
Substrate-specific adapter of a BCR (BTB-CUL3-RBX1) E3 ubiquitin ligase complex that acts as a regulator of the insulin signaling pathway, modulating insulin sensitivity by limiting PIK3R1/p85alpha abundance in adipocytes. Targets PIK3R1, the regulatory subunit of phosphatidylinositol 3-kinase (PI3K), for 'Lys-48'-linked polyubiquitination and proteasome-mediated degradation.
Synonyms: BKLHD1; DKFZP566C134
Tractability: Small molecule: it belongs to a druggable protein family. PROTAC: ubiquitination databases record sites on it; its protein half-life has been measured.
Gene: Protein-coding gene on chromosome 7 (32,868,166 to 32,894,131, reverse strand). Ensembl gene ENSG00000170852.
Subcellular location (Human Protein Atlas): Nucleoli fibrillar center; Nucleoplasm
Gene Ontology:
Molecular function: protein binding; ubiquitin-like ligase-substrate adaptor activity
Biological process: protein K48-linked ubiquitination; protein polyubiquitination; regulation of cellular response to insulin stimulus; proteasome-mediated ubiquitin-dependent protein catabolic process; protein ubiquitination
Cellular component: Cul3-RING ubiquitin ligase complex; cytoplasm; nucleus
Genetic constraint (gnomAD): Loss-of-function variants: 14 observed, 53.48 expected, observed/expected ratio (o/e) 0.26, 90% interval 0.17 to 0.41. The upper end of that interval is the gene's LOEUF score, 0.41, which puts it in group 1 of 6, group 1 being the genes least tolerant of losing a copy. Missense variants: 481 observed, 744.12 expected, observed/expected ratio (o/e) 0.65, 90% interval 0.6 to 0.7. Synonymous variants: 251 observed, 263.48 expected, observed/expected ratio (o/e) 0.95, 90% interval 0.86 to 1.06.
Homologues: Orthologues: macaque KBTBD2 (100% identical), chimpanzee KBTBD2 (99% identical), dog KBTBD2 (99% identical), rabbit KBTBD2 (99% identical), pig KBTBD2 (99% identical), guinea pig KBTBD2 (99% identical), rat Kbtbd2 (99% identical), mouse Kbtbd2 (99% identical), tropical clawed frog kbtbd2 (85% identical), zebrafish kbtbd2 (79% identical). Paralogues in human: KBTBD8 (32% identical), KBTBD12 (24% identical), KLHL28 (23% identical), KLHL41 (22% identical), KBTBD6 (22% identical), KLHL20 (22% identical), KLHL40 (22% identical), KBTBD7 (22% identical), KLHL29 (22% identical), KLHL38 (22% identical), KLHL30 (22% identical), KLHL1 (22% identical), and 42 more.
Diseases named in the same sentence as KBTBD2 in open-access papers:
KBTBD2 is named in the same sentence as 8 diseases in open-access papers, as found by Europe PMC text mining. Sharing a sentence is not in itself a finding about the gene and the disease. The quoted sentences say what the papers report.
diabetes (1 paper, 2024). "KBTBD2 is highly expressed in mouse brain as well as adipose tissue, liver and muscle, and knocking it down in mice resulted in elevated expression of p85α in all of these tissues and a phenotype involving lipodystrophy, hepatic steatosis, insulin resistance, severe diabetes and growth retardation." (PMID 39313616, 2024).
KBTBD2 also shares sentences with these, for which no sentence is quoted: gastric cancer (2 papers); atherosclerosis (1); childhood asthma (1); Hepatic steatosis (1); Insulin resistance (1); lipodystrophy (1); tumor (1).